CD70 (CD70 molecule)
Diseases named in the same sentence as CD70 in open-access papers (continued):
Sharing a sentence is not in itself a finding about the gene and the disease.
non-small cell lung carcinoma (6 papers, 2015 to 2025). A group of at least three distinct histological types of lung cancer, including non-small cell squamous cell carcinoma, adenocarcinoma, and large cell carcinoma. "The role of CD70-mediated immune escape was also demonstrated in non-small cell lung cancer (NSCLC), where CD27+ lymphocytes were found in the tumor microenvironment with a trend towards increased Foxp3 expression and higher CD4/CD8 ratios surrounding CD70+ tumor cells." (PMID 26605342, 2015).
thymic carcinoma (6 papers, 2006 to 2023). Thymic carcinoma (TC) is a type of thymic epithelial neoplasm characterized by a high malignant potential. "CD70-targeting CAR T cell therapy may also be a new candidate for immunotherapy in thymic carcinoma." (PMID 35145909, 2021). "Since approximately 79–88% of thymic carcinomas express CD70, the possibility of evaluating CD70-directed CAR T-cell therapy for advanced thymic carcinomas should be considered in the future." (PMID 35565190, 2022). "The majority of thymic carcinomas (87%) express CD70, whereas all thymic carcinoids and thymomas are CD70-negative." (PMID 38201593, 2023). "Helpful cytologic and immunocytochemical features in making the diagnosis of thymic carcinoma are clear-cut cytological atypia, absence of immature lymphocytes (CD1a+, CD99+), and expression of CD5 and CD70 by neoplastic epithelial cells." (PMID 17498299, 2007).
cervical carcinoma (5 papers, 2023 to 2025). A carcinoma arising from either the exocervical squamous epithelium or the endocervical glandular epithelium. "Notable findings include CD70, FANCD2, PFKP, MORN3, and LEF1, which exhibited strong causal associations and potential relevance in cervical cancer pathogenesis." (PMID 40817807, 2025). "This association signal overlaps with enhancer histone marks in HeLa cervical carcinoma cell line and is in the 3′ regions of CD70." (PMID 36929174, 2023). "TISIDB was employed to examine immune infiltration in cervical cancer, revealing that IDO1 levels exhibit a significantly positive association with ICOS, C10orf54, CD27, CD28, CD70, and other immunostimulatory factors, which negatively regulate the expression of CD276." (PMID 39312339, 2024).
Hodgkins lymphoma (5 papers, 2017 to 2023). A heterogeneous group of malignant lymphoid neoplasms of B-cell origin characterized histologically by the presence of Hodgkin and Reed-Sternberg (HRS) cells in the vast majority of cases. "This analysis highlighted that many KEGG Hodgkin lymphoma pathway genes are jointly induced by TES1 and TES2 signaling in LCLs, including CCL22, BCL3, cRel, IRF4, STAT3, STAT6, and CD70, each of which has prominent roles in Hodgkin lymphoma pathogenesis." (PMID 38009935, 2023). "Interestingly, Abolhassani reported two family members with genetic abnormalities in the CD70- CD27 signaling cascade associated with clinical features of AA, Behcet's disease, recurrent viral pneumonia, central nervous system infection, and Hodgkin lymphoma induced by Epstein–Barr virus." (PMID 35300124, 2022).
primary Sjögren's syndrome (5 papers, 2012 to 2023). "Hypomethylation and over expression of CD70 (TNFSF7) in CD4+ T cells of patients with primary Sjögren's syndrome have been also demonstrated." (PMID 21941583, 2012). "CD70 is overexpressed in SLE, SCLE, SSc, and primary Sjögren’s syndrome (pSS), because of demethylation of its promoter regulatory regions in CD4+ T cells." (PMID 36980827, 2023).
prostate carcinoma (5 papers, 2019 to 2025). A carcinoma that arises from epithelial cells of the prostate gland. "This suggests that FTO overexpression in lung and prostate cancers may impair CD70/CD80-mediated immune activation." (PMID 40565233, 2025). "For instance, cisplatin elevates CD70 in NSCLC, while irradiation boosts CD70 in prostate cancer models." (PMID 40896423, 2025).
atherosclerosis (4 papers, 2017 to 2025). A disease characterized by the build-up of fatty material and calcium deposition in the arterial wall resulting in partial or complete occlusion of the arterial lumen. "Evidence for the role of CD27:CD70 in atherosclerosis is conflicting as ruptured atherosclerotic plaques expressed higher CD70 than those in stable lesions, and CD70 transgenic mice attenuated atherosclerotic development." (PMID 28738836, 2017). "Future studies could evaluate CD70-targeted therapies in atherosclerosis, extending beyond oncology." (PMID 41268556, 2025). "The CD27:CD70 reverse stimulatory immune checkpoint towards APC may be protective for atherosclerosis." (PMID 28738836, 2017). "CD70 deficiency reduced spleen Treg in ApoE−/− mice and CD27 deficiency reduced Treg in solid tumor in mice, suggesting that CD27:CD70 may have an immunosuppressive role in atherosclerosis and tumor growth." (PMID 28738836, 2017). "Unlike conventional costimulatory molecules, CD27/CD70 activates T cells while providing significant protection against atherosclerosis." (PMID 41268556, 2025).
brain cancer (4 papers, 2010 to 2024). A primary or metastatic malignant neoplasm affecting the brain. "We did observe discrepancy with the published literature on the frequency of CD70 expression in nasopharyngeal and brain cancers." (PMID 20664585, 2010). "In contrast, CD70 was notably downregulated in brain cancer." (PMID 39446784, 2024). "Interestingly, a marked trend of a higher colony number in soft agar in CD70-positive (CD70+) cells compared to CD70-negative (CD70–) was identified in 9 ovarian, 5 lung, 2 kidney and 2 brain cancer cell lines in soft agar assays." (PMID 29721188, 2018).
cutaneous T cell lymphoma (4 papers, 2019 to 2025). "SGN-70A inhibited cell growth and induced higher caspase activity in CD70-positive cell lines of cutaneous T-cell lymphoma (CTCL) and patient-derived T-cell lymphoma primary cells." (PMID 33430146, 2021). "Besides the current investigation for AML as mentioned in Section 3.1., anti-CD70 mAb, has also been investigated in heavily pretreated patients with CD70-expressing advanced cutaneous T cell lymphoma." (PMID 33121189, 2020). "ARGX-110, which blocks CD27/CD70 signaling, demonstrated ORR of 23% in heavily pre-treated patients with CD70 expressing advanced cutaneous T cell lymphoma of different subtypes and stages in a phase I/II clinical trial." (PMID 31186046, 2019).
follicular lymphoma (4 papers, 2009 to 2022). Follicular lymphoma is a form of non-Hodgkin lymphoma characterized by a proliferation of B cells whose nodular structure of follicular architecture is preserved. "In follicular lymphoma, there is evidence that TGF-β induces CD70 on T-cells leading to an exhausted phenotype that is associated with worse patient outcomes." (PMID 30446007, 2018).
metastatic melanoma (4 papers, 2013 to 2025). A melanoma that has spread from its primary site to another anatomic site. "As previously documented in the literature, our mIF analysis revealed that metastatic melanoma patients express CD70 and are significantly infiltrated by CD27+T lymphocytes." (PMID 40148586, 2025). "The function of CD70 shows an opposite trend in metastatic melanoma, in which the expression of CD70 is reduced, and CD70+ cancer cell populations are remarkably decreased in metastatic sites, indicating that CD70 may inhibit the ability of tumor metastasis." (PMID 34367975, 2021). "Previous findings from our group showed a positive correlation between the levels of interaction between CD27 and CD70 in the TME and sCD27 concentrations in plasma, prompting us to measure these concentrations in patients with metastatic melanoma." (PMID 40148586, 2025). "Evidence for possible clinical benefit from mobilizing the CD70/CD27 pathway was provided by a recent clinical trial utilizing DCs expressing CD70, CD40L, and constitutively active TLR4 (TriMix-DC) in the treatment of metastatic melanoma patients." (PMID 23450201, 2013).
psoriasis (4 papers, 2020 to 2024). An autoimmune condition characterized by red, well-delineated plaques with silvery scales that are usually on the extensor surfaces and scalp. "The regulatory influence of dendritic cells (DCs) on T cells through the CD70/CD27 signaling pathway may emerge as a significant facet of the inflammatory response in psoriasis." (PMID 38596682, 2024). "The finding that the CD70/CD27 signaling pathway serves as an important link between the two provides a new theoretical basis for unraveling the molecular mechanisms of DCs in psoriasis." (PMID 38596682, 2024). "Therefore, we hypothesized that DCs are involved in the pathogenesis of psoriasis by regulating T cells via the CD70/CD27 signaling pathway." (PMID 38596682, 2024). "Our data indicate that DCs, particularly through the CD70/CD27 pathway, mediate inflammatory responses in psoriasis by influencing other cells, especially T cells." (PMID 38596682, 2024). "Mechanistically, we observed a significant increase in the relative information flow of CD70, SEMA3, and TGF-β in psoriasis skin tissues." (PMID 38596682, 2024). "The results revealed that the outgoing signals of CD70, GRN, ncWNT, and GAS from DCs were significantly increased in psoriasis." (PMID 38596682, 2024). "Notably, consistent with our previous findings, gene expression analysis confirmed the specific expression of CD70 in cluster 1 DCs, providing further support for the significant involvement of the CD70/CD27 signaling pathway in psoriasis development." (PMID 38596682, 2024). "To date, there are no drugs on targeting the CD27:CD70 pathway for the treatment of psoriasis." (PMID 34354596, 2021).
thyroid cancer (4 papers, 2022 to 2025). "Typically, m6A modification tags CD70 mRNA for degradation; thus, METTL3 inhibition allowed CD70 mRNA to accumulate, resulting in increased CD70 protein expression in thyroid cancer cells." (PMID 39874138, 2025). "Using the TISIDB database, we demonstrated that ALDH1A1/A3/B1 had significant negative correlations with immune-stimulating genes, such as CD276, TMEM173, TNFSF9, CD70, TNFRSF25, and CD40 in thyroid cancer." (PMID 35280765, 2022).
acute GVHD (3 papers, 2024 to 2025). "CD4+ and CD8+CD70+ T-cell numbers increased by ninefold and fourfold, respectively, during acute GVHD (aGVHD) and displayed an oligoclonal TCR repertoire." (PMID 39028952, 2024). "A comparison of skin tissue biopsies from patients with acute GVHD vs those without revealed a significant increase in the proportion of CD70+ subgroups within CD8+ T cells, surpassing the increase observed in CD70+ subgroups within CD4+ T cells." (PMID 39840040, 2024).
chronic lymphocytic leukemia (3 papers, 2006 to 2023). "Co-expression of CD70 and CD27 is also present on AML and B cell acute lymphoblastic leukemia (B-ALL) blasts, on malignant B cells of chronic lymphocytic leukemia (B-CLL) and subtypes including hairy cell leukemia and its prolymphocytic variant." (PMID 34991665, 2022).
Cognitive impairment (3 papers, 2023 to 2024). Abnormal cognition is characterized by deficits in thinking, reasoning, or remembering. "Increased IL-6 and CD70 were associated with cognitive impairment, highlighting the role of CD70 in neuroinflammation in the CNS." (PMID 37445634, 2023). "That study also explored the potential role of inflammatory proteins such as CD70 which have previously been associated with central nervous system (CNS) inflammation, as both IL‐6 and CD70 were raised in patients with cognitive impairment at 1‐year follow‐up." (PMID 37904690, 2023). "Additionally, IL-6 and the CD70 molecule were significantly increased in the moderate with cognitive impairment cluster compared with the mild cluster." (PMID 37368949, 2024).
colon carcinoma (3 papers, 2018 to 2025). "Clinical studies have identified CAFs co-expressed CD70 and periostin (POSTN) as associated with advanced pT stage in colon cancer or peritoneal metastasis, suggesting a promising therapeutic target." (PMID 40535136, 2025).
mesothelioma (3 papers, 2019 to 2025). A usually malignant and aggressive neoplasm of the mesothelium which is often associated with exposure to asbestos. "In addition, the majority of samples from oesophageal carcinoma (66.7%, N = 12) and mesothelioma (62.5%, N = 8) showed CD70 positivity." (PMID 31652572, 2019).
Thrombocytopenia (3 papers, 2019 to 2025). A reduction in the number of circulating thrombocytes. "In conclusion, while CD70 would appear to be a promising target in the treatment of R/R NHL, the applicability of SGN-CD70A is limited by the frequency and severity of thrombocytopenia, despite the long-term of response with limited drug exposure." (PMID 30132271, 2019).
antibody deficiency (2 papers, 2017 to 2021). "This was in line with the current observations in our CD70-deficient proband that besides hypogammaglobulinemia and reduced proportion of switched memory B cells, the patient had an impaired ability of B cells to secrete IgG and IgA in vitro." (PMID 33996677, 2021).
Arthritis (2 papers, 2022). Inflammation of a joint. "In a collagen-induced arthritis model, treatment with CD70-blocking antibody resulted in marked improvements in disease severity and a significant reduction in the production of autoantibodies." (PMID 35216458, 2022). "Anti-CD70 antibodies lowered the antibody titer and decreased joint disease's severity in murine collagen-induced arthritis." (PMID 35300124, 2022).
colitis (2 papers, 2021 to 2022). Inflammation of the colon. "Colitis was prevented along with a decrease in colitis-associated Th1 cytokines in a mouse model using anti-CD70 antibodies." (PMID 35300124, 2022). "Evidence from two mouse models of colitis suggests that binding of CD27 to its ligand CD70 on antigen-presenting cells plays a role in mediating colitis." (PMID 34722568, 2021).
colorectal tumor (2 papers, 2016 to 2020). "Here, several human colorectal tumor cell lines were exposed to radiation (0–10 Gy) in vitro and changes in the expression of molecules costimulatory to effector T cells (4-1BBL, OX-40L, CD70, ICOSL) were examined by flow cytometry." (PMID 26872462, 2016). "We found OX-40L and 4-1BBL to be the most consistently upregulated proteins on the surface of colorectal tumor cells post-IR while ICOSL and CD70 remained largely unaltered." (PMID 26872462, 2016). "The lack of CD70, CD80, or CD86 expression on ILCs in colorectal tumors could, therefore, be the consequence of signals counteracting the effect of inflammasome-associated cytokines in the local microenvironment." (PMID 32341343, 2020).
Ewing sarcoma (2 papers, 2015 to 2023). A small round cell tumor that lacks morphologic, immunohistochemical, and electron microscopic evidence of neuroectodermal differentiation. "Ewing sarcoma cDCs showed significantly lower percentages of CD83-, CD86-, and TNFSF9-expressing cells and Ewing sarcoma Mφ had significantly lower CD70-, CD80-, CD83-, and TNFSF9-expressing cells, than neuroblastoma." (PMID 37823774, 2023). "In contrast, CD70 was detected on few Ewing sarcoma cell lines (5/15) and was virtually absent from neuroblastoma (1/7) and rhabdomyosarcoma cell lines (0/5)." (PMID 25792975, 2015).
hepatitis B (2 papers, 2022 to 2023). "Whether the potential of CD70 co-expression in a therapeutic vaccination setting against hepatitis B is underestimated by the choice of the HBV core instead of the more potent HBV surface antigen as a model was not assessed and would be an interesting subject for further investigation." (PMID 36851121, 2023).
lung adenocarcinoma (2 papers, 2015 to 2024). A carcinoma that arises from the lung and is characterized by the presence of malignant glandular epithelial cells. "In a primary lung adenocarcinoma and a small intestine metastasis from the same patient, CD70 staining of equivalent intensity with clear membranous accentuation in more than 80% of the tumor cells was observed." (PMID 25951351, 2015).
lung fibrosis (2 papers, 2015 to 2025). "Moreover, It has been shown that up-regulation of CD27 activity on human T cells precisely activate CD70 activity on fibroblasts to reduce collagen deposition and inhibit pulmonary fibrosis by reducing fibroblast proliferation." (PMID 40433386, 2025).
lymphoproliferative disorders (2 papers, 2017 to 2020). "Humans deficient in CD27 or CD70 are at risk of lymphoproliferative disorders associated with Epstein-Barr virus (EBV) as a result of reduced proliferation of EBV-specific T cells." (PMID 29198913, 2017).
myelodysplastic syndrome (2 papers, 2024 to 2025). A clonal hematopoietic disorder characterized by dysplasia and ineffective hematopoiesis in one or more of the hematopoietic cell lines. "These include blastic plasmacytoid dendritic cell neoplasm (BPDCN), targeted through CD123; Waldenströms macroglobulinemia (WM), addressed through the NKG2D ligand (NKG2DL); and myelodysplastic syndromes (MDS), which are targeted using CD70." (PMID 40149002, 2025).
Oral Cancer (2 papers, 2014 to 2022). "Studies have reported that CD70 is highly expressed in oral cancer, and its specific CAR-T cells can specifically recognize and effectively eliminate CD70-positive HNSCC cells." (PMID 35299954, 2022).
primary immunodeficiencies (2 papers, 2018 to 2021). "Prospective data collection on HSCT in ITK deficiency and other EBV prone primary immunodeficiencies, as CD27 or CD70 deficiency is highly warranted." (PMID 29867957, 2018).
psoriatic arthritis (2 papers, 2022 to 2023). Joint inflammation associated with psoriasis. "In agreement with our results, CD70 expression was upregulated on CD4+ Th cells isolated from the synovial fluid of patients with psoriatic arthritis." (PMID 35300124, 2022).
T-cell immunodeficiency (2 papers, 2022 to 2023). A broad classification of disorders that affect the cell-mediated aspect of the immune response. "Continuous stimulation of CD27 by constitutive expression of CD70 on B cells resulted in increased apoptosis and depletion in NK cells or T-cell immunodeficiency." (PMID 37180119, 2023).
thymoma (2 papers, 2021 to 2023). A neoplasm arising from the epithelial cells of the thymus. "The current study showed a consistent expression of CD70 in the normal thymic medulla adjacent to the tumor, which was also retained in <1% of tumor cells observed in the medullary island of type B1 thymoma." (PMID 35145909, 2021). "The mRNA extracted from frozen tissues of TSCC (n = 12) and thymoma (type A: n = 4; type B3: n = 5) was quantified using RT-PCR for CD70." (PMID 35145909, 2021). "The expression levels of CD70 in TSCC were significantly higher than those observed in thymoma (p < 0.001)." (PMID 35145909, 2021). "Although the percentage of CD70 positive cells in each case was rather small, the sensitivity and specificity of CD70 in distinguishing TSCC from thymoma are comparable with those of CD5 and CD117." (PMID 35145909, 2021). "In the present study, we performed an IHC analysis for CD70 in TSCC and compared the results with those obtained in thymoma and LSCC." (PMID 35145909, 2021). "We also demonstrated good agreement with IHC score and mRNA expression levels of CD70 by quantitative RT-PCR in TSCC and thymoma." (PMID 35145909, 2021). "On the other hand, all cases of thymoma and thymic carcinoid were negative for CD70." (PMID 35145909, 2021). "In contrast, all thymoma and thymic carcinoid cases were CD70-negative." (PMID 35145909, 2021). "Using IHC analysis in a limited number of frozen TSCC sections, we previously demonstrated that positive staining for CD70 was observed frequently in neoplastic epithelial cells of TSCC, unlike in those of thymoma and LSCC." (PMID 35145909, 2021).